CDK5RAP3 (CDK5 regulatory subunit associated protein 3)
Diseases named in the same sentence as CDK5RAP3 in open-access papers (continued):
Sharing a sentence is not in itself a finding about the gene and the disease.
gastric cancer (continued). "Accordingly, we speculate that part of the potential mechanism by which CDK5RAP3 mediates gastric cancer cell migration, invasion and EMT is at least accomplished by regulating the expression of MMP2 in macrophages." (PMID 35999359, 2023). "Under the condition of coculture of macrophages, the downregulation of CDK5RAP3 resulted in a significant upregulation of the expression levels of N-cadherin, vimentin and Snail mRNA in gastric cancer, while the expression level of E-cadherin was significantly reduced." (PMID 35999359, 2023). "BGC-823 gastric cancer cells with stable overexpression or knockdown of CDK5RAP3 were created." (PMID 35999359, 2023). "Our results imply that CDK5RAP3 may be involved in the regulation of immune activity in the tumour microenvironment and is expected to become a potential immunotherapy target for gastric cancer." (PMID 35999359, 2023). "Therefore, we used public databases to search for proteins related to the GFR signalling pathway and CDK5RAP3 and attempted to identify biological prognostic indicators for gastric cancer." (PMID 36387125, 2022). "Based on our previous study and an examination of public databases, this study found that the expression of the UFM1 and CDK5RAP3 genes are downregulated synchronously in gastric cancer patients with poor prognosis and that an interaction occurs between the UFM1 and CDK5RAP3 proteins." (PMID 36387125, 2022). "Therefore, in patients with gastric cancer, we assessed the relationship between relevant clinicopathological parameters and overall survival by detecting the CDK5RAP3 and UFM1 expression levels." (PMID 36387125, 2022). "We also used Western blotting to detect CDK5RAP3 and UFM1 expression in the cancerous and paracancerous tissues of 43 gastric cancer patients and simultaneously detected the mRNA levels of CDK5RAP3 and UFM1 in the tumour tissues of 48 patients with gastric cancer." (PMID 36387125, 2022). "Therefore, we investigated the correlation between UFM1 and CDK5RAP3 expression and the prognosis of gastric cancer using public databases." (PMID 36387125, 2022). "In the stomach, CDK5RAP3 also functions as a tumor suppressor both in gastric cancer and in GNEC." (PMID 34722315, 2021). "Our recent work revealed that CDK5RAP3 inhibits phosphorylation of AKT at Ser473 in gastric cancer." (PMID 31728130, 2019). "Our results demonstrate that CDK5RAP3 can interact with MCM6 and prevent MCM6 from translocating into the nucleus, which may be a potential mechanism through which CDK5RAP3 negatively regulates the proliferation of gastric cancer." (PMID 31528213, 2019). "To further investigate the role of CDK5RAP3 in gastric cancer, we performed MS to search for other proteins that may interact with CDK5RAP3 in HGC-27 and 293T cells." (PMID 31528213, 2019). "What's more, in our manuscript we focused on the relationship between MCM6, CDK5RAP3, clinicopathological data and prognosis of the patient, thus we just selected the most representative gastric cancer cell lines of HGC-27 and AGS to find some change in phenotype." (PMID 31528213, 2019). "In summary, our results clarified that CDK5RAP3 interacts with MCM6 and prevents MCM6 from entering the nucleus, thereby influencing the proliferation of gastric cancer, which provides a new aspect of how CDK5RAP3 may suppress tumor proliferation." (PMID 31528213, 2019). "Our previous study demonstrated that CDK5RAP3 expression was downregulated in gastric cancer, which correlated with poor prognosis, and that CDK5RAP3 could inhibit Wnt/β-catenin signaling by blocking GSK-3β phosphorylation at Ser9." (PMID 29540196, 2018). "Previously, we have investigated the role of CDK5RAP3 in gastric cancer." (PMID 29540196, 2018). "However, when p-AKT (Ser473) expression was high, gastric cancer patients with low CDK5RAP3 expression had a poorer prognosis than those with high CDK5RAP3 expression (P < 0.05)." (PMID 29540196, 2018).
gastric cancer (continued). "Based on the correlation result between CDK5RAP3 and TAMs, we hypothesized that CDK5RAP3 may affect the infiltration and polarization of TAMs in the microenvironment, thereby affecting the prognosis of gastric cancer patients." (PMID 35999359, 2023). "However, loss of normal regulation of cell proliferation and apoptosis may lead to tumour or cancer, and CDK5RAP3 was reported related to renal cancer, gastric cancer, colorectal cancer and others." (PMID 35509151, 2022). "Further analysis of related factors showed that the CDK5RAP3 and UFM1 coexpression was strongly linked to the invasive depth, lymph node metastasis and TNM stage, indicating that the two proteins are closely related to tumour invasion and migration in gastric cancer." (PMID 36387125, 2022). "However, how CDK5RAP3 suppresses the proliferation of gastric cancer remains poorly understood." (PMID 31528213, 2019). "Importantly, we found that CDK5RAP3 was a significant regulator of GSK3β phosphorylation in gastric cancer, leading to the subsequent degradation of β-catenin and influencing the prognosis of gastric cancer patients." (PMID 29540196, 2018). "We obtained the gastric cancer mRNA expression matrix from the TCGA database, and CIBERSORT was used to calculate the relative proportion of CDK5RAP3-related immune cell types." (PMID 35999359, 2023). "After the mice were sacrificed, western blotting was used to verify the expression of CDK5RAP3 in the xenograft tumours with BGC-823 and AGS gastric cancer lines with different treatments." (PMID 35999359, 2023). "The downregulation of CDK5RAP3 in gastric cancer cells further increased the expression of MMP2 in macrophages, while overexpression of CDK5RAP3 significantly reduced the expression of MMP2." (PMID 35999359, 2023). "In contrast, the levels of IL4 and IL10 in the culture supernatant increased significantly in CDK5RAP3-depleted gastric cancer cells, while PDTC reduced the upregulation of IL4 and IL10 levels induced by gastric cancer cells with low CDK5RAP3 expression." (PMID 35999359, 2023). "Flow cytometry analysis showed that the overexpression of CDK5RAP3 in gastric cancer cells significantly reduced the number of CD206+ TAMs differentiated from THP-1, while the low expression of CDK5RAP3 significantly increased the proportion of CD206+ TAMs." (PMID 35999359, 2023). "In a recent study on the molecular mechanism of CDK5RAP3, we demonstrated that CDK5RAP3 is inhibited by ERK signalling and negatively regulates the self-renewal of gastric cancer stem-like cells (CSCs) and EMT." (PMID 35999359, 2023). "We compared the accuracy of CDK5RAP3 or UFM1 expression, as well as combined CDK5RAP3 and UFM1 expression and TNM staging, in predicting gastric cancer survival using ROC curve analysis." (PMID 36387125, 2022). "As a result, in clinical practice, the coexpression of CDK5RAP3 and UFM1 can be used in cooperation with TNM staging to effectively guide treatment and follow-up of patients with gastric cancer." (PMID 36387125, 2022). "IHC staining score was used to analyse CDK5RAP3 and UFM1 protein expression in paraffin-embedded gastric cancer samples from 124 patients." (PMID 36387125, 2022). "To date, few studies have investigated the combined expression levels of CDK5RAP3 and UFM1 and its prognostic significance in gastric cancer." (PMID 36387125, 2022). "The relationship between the CDK5RAP3 and UFM1 expression and the prolonged outcomes of patients who underwent gastric cancer (GC) surgery was investigated." (PMID 36387125, 2022). "Multivariate analysis indicated that the coexpression level of CDK5RAP3 and UFM1, as well as TNM stage were both independent predictive variables for patient prognosis with gastric cancer." (PMID 36387125, 2022).
gastric cancer (continued). "In univariate analysis, low CDK5RAP3 expression was linked to a poor prognosis, and high UFM1 expression was linked to a better survival rate in gastric cancer patients, indicating that both CDK5RAP3 and UFM1 play a tumour suppressor role in gastric cancer." (PMID 36387125, 2022). "In comparison to the conventional TNM staging’s forecast accuracy, combining CDK5RAP3 and UFM1 expression with TNM greatly improved the accuracy of predicting gastric cancer patient survival." (PMID 36387125, 2022). "CDK5RAP3 is also confirmed to interact with minichromosome maintenance 6 (MCM6) and hinder its translocation into the nucleus, resulting in the inhibition of gastric cancer cell proliferation." (PMID 34722315, 2021). "Previously, we demonstrated that CDK5RAP3 represses AKT phosphorylation, which promotes GSK-3β phosphorylation in gastric cancer." (PMID 31728130, 2019). "Prognostic analysis showed that the combined expression of CDK5RAP3 and MCM6 was an independent prognostic factor correlating with the overall survival of gastric cancer patients." (PMID 31528213, 2019). "Recently, low expression of CDK5RAP3 and its partner DDRGK1 has been correlated with poor prognosis of gastric cancer." (PMID 31061682, 2019). "Another study showed that low expression of CDK5RAP3 and DDRGK1 are related to poor prognosis in patients with gastric cancer." (PMID 31528213, 2019). "In summary, our results clarified that CDK5RAP3 blocks AKT phosphorylation to inhibit β-catenin signaling, thereby influencing the biological behavior and prognosis of gastric cancer, which supplements the mechanism described in our previous study." (PMID 29540196, 2018). "In this study, we found that CDK5RAP3 blocked AKT phosphorylation to inhibit β-catenin signaling, which promoted gastric cancer cell proliferation, invasion and migration." (PMID 29540196, 2018). "CDK5RAP3 repressed AKT phosphorylation, which promoted GSK-3β phosphorylation, thereby suppressing β-catenin protein expression and, consequently, gastric cancer." (PMID 29540196, 2018). "CDK5RAP3 expression was confirmed using Western Blotting, and the effect of AKT on CDK5RAP3 function in gastric cancer cells was assessed using AKT siRNA." (PMID 29540196, 2018). "Our results demonstrated that CDK5RAP3 negatively regulates the Wnt/β-catenin signaling pathway by repressing AKT phosphorylation, which leads to better survival of patients with gastric cancer." (PMID 29540196, 2018). "Moreover, in combination of UFM1, CDK5RAP3 and TNM (tumor, node, metastasis) stages increased the accuracy of prognosis prediction in gastric cancer patients." (PMID 39247188, 2024). "Among the six main immune infiltrating cells, CDK5RAP3 only has a significant negative correlation with the level of macrophage infiltration in gastric cancer." (PMID 35999359, 2023). "In summary, CDK5RAP3 is involved in the regulation of the immune activity state of the TME, and it is expected to become a promising biomarker for the treatment and prognosis of gastric cancer." (PMID 35999359, 2023). "In order to explore the effect of MMP2 inhibitor on gastric cancer cells with downregulation of CDK5RAP3, we set up a group of gastric cancer cells with downregulation of CDK5RAP3 without macrophage co-culture." (PMID 35999359, 2023). "In vivo bioluminescence imaging showed that low expression of CDK5RAP3 significantly increased the in-situ proliferation of gastric cancer cells compared with the control group, while the MMP2 inhibitor reversed the increase in proliferation induced by low CDK5RAP3 expression." (PMID 35999359, 2023). "UFM1, UfBP1, and CDK5RAP3 expression is also downregulated in gastric cancer compared with respective adjacent non-tumor tissues; this downregulation is a poor prognostic factor for affected patients." (PMID 37947621, 2023).
gastric cancer (continued). "Although some studies have suggested that UFM1 binds to CDK5RAP3, the expression of the two proteins and their effects on the prolonged survival in gastric cancer have not been documented yet." (PMID 36387125, 2022). "Thereby, we considered that CDK5RAP3 and UFM1 may play a coordinated role in inhibiting the gastric cancer invasion and metastasis." (PMID 36387125, 2022). "Therefore, combination of the CDK5RAP3 and UFM1 expression can improve the capacity to forecast the survival outcomes of patients with gastric cancer." (PMID 36387125, 2022). "Maybe it is possible to build a more precise model combining CDK5RAP3, UFM1 and TNM staging to predict 5-year survival of gastric cancer after surgery." (PMID 36387125, 2022). "Additionally, we found that the functions of CDK5RAP3 and UFM1 in gastric cancer were positively correlated." (PMID 36387125, 2022). "There are few studies investigating the role of MCM6 in gastric cancer, and the interaction of CDK5RAP3 and MCM6 had not been investigated." (PMID 31528213, 2019). "We discovered that CDK5RAP3 could interact with MCM6 and prevent it from translocating into the nucleus in gastric cancer." (PMID 31528213, 2019). "In addition, the absence of CDK5RAP3 in gastric cancer cells allows macrophages to secrete more MMP2 to promote the epithelial-mesenchymal transition (EMT) process of gastric cancer cells, thereby enhancing the invasion and migration ability." (PMID 35999359, 2023). "In addition, the absence of CDK5RAP3 in gastric cancer cells induces macrophages to secrete high levels of MMP2, thereby promoting the migration and invasion of gastric cancer cells." (PMID 35999359, 2023). "In our previous researches, we found that CDK5RAP3 can inhibit the phosphorylation of AKT in gastric cancer, thereby inhibiting the GSK-3β mediated phosphorylation, degrading β-catenin and acting as a tumour suppressor in the occurrence and progression of gastric cancer." (PMID 36387125, 2022). "Furthermore, knockdown of MCM6 reversed the effect of CDK5RAP3 downregulation in HGC-27 and AGS cells, which indicates that MCM6 could mediate the tumor suppressor role of CDK5RAP3 in gastric cancer." (PMID 31528213, 2019). "There have been many breakthroughs regarding the upstream regulatory mechanisms of AKT; however, whether AKT/GSK-3β/β-catenin signaling is regulated by CDK5RAP3 in gastric cancer has not been explored." (PMID 29540196, 2018). "Consequently, these results indicated that the lack of CDK5RAP3 in gastric cancer enhances the EMT process of gastric cancer cells by promoting the secretion of MMP2 by TAMs in vitro, thereby enhancing the proliferation, invasion, and migration ability of gastric cancer cells." (PMID 35999359, 2023).
hepatocellular carcinoma (13 papers, 2011 to 2025). A malignant tumor that arises from hepatocytes. "Low levels of CDK5RAP3 are associated with a subset of head and neck squamous cell carcinomas (HNSCCs) and hepatocellular carcinomas (HCCs) as well as with poor survival." (PMID 35053516, 2022). "CDK5 kinase regulatory subunit-associated protein 3 (CDK5RAP3) in hepatocellular cancer and hepatocyte growth factor (HGF) and follicle-stimulating hormone (FSH) in ovarian cancer activate PAK4 to promote cell migration." (PMID 25975262, 2015). "In contrast, additional studies indicate that CDK5RAP3 appears to promote tumorigenesis because it is overexpressed in lung adenocarcinoma, hepatocellular carcinoma, breast cancer and cervical carcinoma, and has an oncogenic roles in these cancers." (PMID 34722315, 2021). "In hepatocellular cancer, CDK5RAP3 was reported to promote metastasis through PAK4 activation." (PMID 31061682, 2019). "However, data from hepatocellular cancer indicates CDK5RAP3 promotes metastasis through the activation of PAK4." (PMID 31061682, 2019). "Studies have shown that CDK5RAP3 plays a significant role in diseases such as hepatocellular carcinoma (HCC), gastric cancer, colon cancer, and gastric neuroendocrine carcinoma." (PMID 40868283, 2025). "The role of CDK5RAP3 in hepatocellular carcinoma (HCC) remains unclear." (PMID 40868283, 2025).
head and neck squamous cell carcinoma (9 papers, 2011 to 2021). A squamous cell carcinoma that arises from any of the following anatomic sites: lip and oral cavity, nasal cavity, paranasal sinuses, pharynx, larynx, and salivary glands. "Loss of CDK5RAP3 protein was observed in approximately 30% of human head and neck squamous cell carcinomas (HNSCC), and in these tumors, CDK5RAP3 expression inversely correlated with expression of a subset of NF-kB target genes." (PMID 33182370, 2020). "CDK5RAP3 has been shown to function as a tumor suppressor in head and neck squamous cell carcinomas (HNSCCs), and forced expression of CDK5RAP3 suppresses NF-kB activity." (PMID 29540196, 2018). "CDK5RAP3 was initially considered as a putative tumor suppressor since it is found to be markedly reduced in 32% of primary head and neck squamous cell carcinoma (HNSCC), and inhibits cellular transformation and tumor growth in vitro and in vivo." (PMID 34722315, 2021). "CDK5RAP3 has been reported to bind with RelA and suppress the NF-κB pathway through the LXXLL/leucine zipper-containing alternative reading frame (ARF) to repress head and neck squamous cell carcinoma." (PMID 31061682, 2019).
breast cancer (5 papers, 2011 to 2022). A primary or metastatic malignant neoplasm involving the breast. "Consistently, gene expression data analysis showed CDK5RAP3 overexpression in breast cancer is associated with poorer survival." (PMID 35053516, 2022). "CDK5RAP3 expression is linked to breast cancer survival and its genetic variations are associated with BRCA1/2 mutation carriers." (PMID 35053516, 2022). "Consistent with this cellular phenotype, analysis of transcriptomic data revealed an association between low CDK5RAP3 tumor expression and poor survival of breast cancer patients." (PMID 35053516, 2022). "Additional analysis also showed an association between poor survival rates and low CDK5RAP3 expression in basal, luminal A and luminal B breast cancer patients." (PMID 35053516, 2022). "In this study, a screening for physical interactors of BRCA2 identified CDK5RAP3, which emerged as a critical regulator of DNA DSB repair that is associated with breast cancer outcomes." (PMID 35053516, 2022). "Our data connecting CDK5RAP3 to the BRCA2 pathway suggest a potential therapeutic approach for breast cancer." (PMID 35053516, 2022). "Our results uncover CDK5RAP3 as a critical player in DNA repair and breast cancer outcomes." (PMID 35053516, 2022). "The functional connection between CDK5RAP3 and breast cancer may be extended to cancer etiology, as suggested by the results of the association study between common genetic variants and cancer development in BRCA1/2 mutation carriers." (PMID 35053516, 2022). "CDK5RAP3 thus emerges as a potential prognostic biomarker for breast cancer." (PMID 35053516, 2022). "To further assess the prediction that low CDK5RAP3 levels promote tumor chemoresistance, we computed the expression correlation between CDK5RAP3 and previously defined signatures of chemoresistance and/or DNA damage resistance using breast cancer data from The Cancer Genome Atlas." (PMID 35053516, 2022). "Besides, CDK5RAP3 in breast cancer cells is reported to positively regulates the transcriptional activity of signal transducer and activator of transcription 3 (STAT3), an oncogenic transcription factor, to trigger its tumorigenic phenotypes." (PMID 34722315, 2021). "CDK5RAP3 is also observed to enhance the clonogenesis and migration in breast cancer cells." (PMID 34722315, 2021). "In addition, the observed DNA damage resistance and reduced genomic instability in CDK5RAP3-depleted cells may contribute to increased tumor aggressiveness and progression in breast cancer patients (as seen in Km plot analysis)." (PMID 35053516, 2022). "We also found that CDK5RAP3 is related to mammary tumours (data not shown)." (PMID 35509151, 2022).